FOXM1 (forkhead box M1)
Diseases named in the same sentence as FOXM1 in open-access papers (continued):
Sharing a sentence is not in itself a finding about the gene and the disease.
tumor (continued). "Interestingly, the correlation of FOXM1 expression and Ki-67 staining reveals a low expression in the G1-graded tumors and FOXM1 expression significantly increases in the tumor subgroup with a Ki-67 value higher than 2-4% (p=0.000)." (PMID 25797272, 2015). "However, FoxM1 inhibition combined with irradiation significantly impeded tumor growth and prolonged survival of tumor bearing mice." (PMID 26444992, 2015). "In clinical settings, FOXM1 has been shown to be upregulated in a range of different tumour types." (PMID 26576650, 2015). "The second subcategory contains a reciprocal relationship between normal oesophagous and OAC where expression is reduced in the tumour samples, and hence shows an anti-correlation with FOXM1 expression, despite representing direct targets (eg AGFG2 and CCDC85C)." (PMID 25889361, 2015). "Administration of 5 mg/kg TS every other day impaired tumor growth and reduced FOXM1 expression." (PMID 26011724, 2015). "Again, the FOXM1 target gene cohort was clustered according to expression similarities amongst the genes themselves and also amongst patient samples and a good separation between normal and tumour samples was obtained." (PMID 25889361, 2015). "First, we assessed the clinical relevancy of FOXM1 in GEP-NEN tumor specimens." (PMID 25797272, 2015). "For tumor cells metastatic programs, the expression of FOXM1 may regulate a series of interrelated events including the expession of caveolin-1, VEGF, MPP-2 and MPP-9, which are important to epithelial–mesenchymal transition (EMT), angiogenesis and metastasts." (PMID 25935853, 2015). "A mounting body of evidence notes that FOXM1 is a critical regulator of both the G1/S and G2/M transitions through the cell cycle progression, which is required for proliferative expansion during tumor progression." (PMID 25935853, 2015). "Forkhead Box M1 (FoxM1) is a master regulator of tumor metastasis." (PMID 26264222, 2015). "PLK1 and FOXM1 co-expression was demonstrated in 6/8 (75 %) tumours when analysed by RT-PCR." (PMID 26576650, 2015). "Besides the cell proliferation capability of FOXM1, aberrant regulation of FOXM1 is a leading factor of malignancy tumor metastasis." (PMID 25935853, 2015). "In addition, the FOXM1 is abundantly expressed in human NSCLCs and it transcriptionally induces the expression of genes essential for proliferation of tumor cells." (PMID 25788272, 2015). "As such, doxycycline could be re-purposed clinically as a ‘safe’ mitochondrial inhibitor, to target FOXM1 and mitochondrial biogenesis in CSCs, to prevent tumor recurrence and distant metastasis, thereby avoiding patient relapse." (PMID 26087310, 2015). "Tumor cells may hijack the negative regulation of FOXM1 by ROS in order to evade cytotoxic effects of chemotherapeutic drugs and to promote survival of resistant clones." (PMID 26000093, 2015). "FoxM1 is regarded as a master regulator of tumor metastasis." (PMID 26264222, 2015). "In addition, down-regulation of FOXM1 in CAOV3 xenografts significantly reduced tumor and ascites formation, metastasis, and expression of FOXM1 target genes involved in cell proliferation, migration, or invasion." (PMID 26299613, 2015). "The relative expression of the three FOXM1 isoforms is in agreement with our primary tumor data." (PMID 26243836, 2015). "In BC the levels of FOXM1 correlate positively with the tumor grade and with poor prognosis." (PMID 24866763, 2014). "Our data indicate that targeting FOXM1 increases apoptosis and inhibits tumor growth." (PMID 25093142, 2014). "Next, we determined the effects of FOXM1 overexpression on tumor cell metastasis." (PMID 24885308, 2014). "So, given the similarity between the progress of tumor progression and embryo implantation, we presume that FoxM1 may be an indispensable factor in embryo implantation." (PMID 25522167, 2014). "It has been reported that FOXM1 promotes tumor progression in malignancies." (PMID 24885308, 2014).
tumor (continued). "Next, we determined the effects of FOXM1 silencing on tumor cell metastasis." (PMID 24885308, 2014). "The widespread evidence of the importance of FOXM1 in various tumor types has led to speculation that it might prove to be a useful drug target in a wide spectrum of diseases." (PMID 23365673, 2013). "FoxM1 has been reported to modulate drug sensitivity and resistance in various tumor types." (PMID 23467617, 2013). "Indeed, the depletion of FoxM1 in various mouse models suppresses cell division and thus tumor formation." (PMID 23386997, 2013). "Moreover, FoxM1 is also repressed by miR-370, a tumor suppressor miRNA frequently silenced in acute myeloid leukemia." (PMID 23467617, 2013). "In summary, the results from this work demonstrated that miR-149 might act as a tumor suppressor in NSCLC cells via inhibiting the expression of FOXM1." (PMID 23762558, 2013). "Taken together, these findings support the hypothesis that FoxM1 plays an important role in tumor metastasis of NSCLC." (PMID 23536876, 2013). "Finally, we found that one of the cellular mechanisms by which FoxM1 promotes tumor metastasis is through inducing epithelial-mesenchymal transition (EMT) program." (PMID 23536876, 2013). "Indeed, recent studies have already shown that targeting FoxM1 sensitizes different tumor cells to those DNA damaging treatments." (PMID 23467617, 2013). "In our previous study, we have demonstrated that FoxM1 could mediate the proliferation of SCLC cell lines, which may be associated with the advanced tumor stage." (PMID 23536876, 2013). "Our group also certified that miR-370 is downregulated in AML and is involved in cell proliferation by directly targeting the 3′ UTR of Forkhead box M1 (FoxM1), the key positive transcriptional factor in the cell cycle and found overexpressed in many tumor types." (PMID 24148180, 2013). "FoxM1 is a uniquely suitable target for therapeutic intervention in many tumor types." (PMID 23857410, 2013). "There was no clear association between the presence of FoxM1 mRNA and age, gender, tumor burden or FAB subtypes (data not shown)." (PMID 22900969, 2012). "Taken together, miR-370 may function as a tumor suppressor by targeting FoxM1, and the epigenetic silence of miR-370 thus leads to derepression of FoxM1 expression and consequently contributes to AML development and progression." (PMID 22900969, 2012). "Moreover, inhibition of ERK activity by U0126 or PD98059, or decreased FOXM1 expression by Thiostrepton significantly inhibited cell migration/invasion, tumor growth in vitro and in vivo." (PMID 23285101, 2012). "The molecular mechanism underlying FoxM1 signaling-mediated induction of tumor growth has not been completely elucidated." (PMID 21857934, 2011). "As research in tumor-targeted siRNA delivery steadily advances, we examine the functional ability of anti-FoxM1 siRNA to induce suppression of FOXM1 in tumors, as a proof-of-principle for the potential of anti-FoxM1 siRNA as a therapeutic agent." (PMID 22203467, 2011). "Regarding the tumor subtype, the expression of FOXM1 was highly correlated with endometriod adenocarcinoma (P<0.05), in which 74.07% of cases demonstrated over-expression of FOXM1." (PMID 21858223, 2011). "Therefore, Foxm1 is critical for the proliferation of tumor cells during the expansion of lung tumors." (PMID 19672312, 2009). "Finally, we demonstrated that a conditional deletion of Foxm1 in pre-existing lung tumors dramatically reduced tumor growth in the lung." (PMID 19672312, 2009). "Moreover, the present data suggest that the main role of Foxm1 in epithelial cells occurs during tumor progression/expansion." (PMID 19672312, 2009). "Therefore, we wanted to find out whether FOXM1 signature is also seen among plastic signature genes and thus upregulated in patient metastatic tumor samples." (PMID 40115748, 2025).
tumor (continued). "Moreover, we subcutaneously injected BEL-7402 cells with WTAP knockdown (shWTAP), WTAP knockdown together with FOXM1 overexpression (shWTAP+FOXM1), or the vehicle control (shCON) into nude mice and determined the growth of tumor in vivo by monitoring tumor size weekly." (PMID 40846737, 2025). "FOXM1 may also be a therapeutic target in tumour progressing following PI3Kαi or AKTi treatment." (PMID 40263319, 2025). "In addition to tumor cell proliferation, the role of FOXM1 has been reported in several cellular processes including, inflammation, apoptosis hindrance, angiogenesis and metastasis promotion, therapy resistance, renewal of stem cells and maintenance of mitotic spindle integrity." (PMID 39762471, 2025). "Additionally, FOXM1 supports the maintenance of OC stem cell properties and contributes to metabolic reprogramming within the tumor microenvironment." (PMID 40746724, 2025). "However, further studies are needed to explore the activation of other pathways and determine whether the observed anti-tumor effects are attributable to FOXM1 inhibition." (PMID 40612352, 2025). "Furthermore, USP39 knockdown resulted in the inhibition of tumor growth in xenografts in nude mice, accompanied by a reduction in the expression levels of forkhead box protein M1 (FoxM1) and its target genes polo-like kinase 1, cyclin B1, and centromere protein A." (PMID 40990019, 2025). "Thus, targeting FOXM1 in tumor tissue using approaches such as tumor-targeted nanocarriers may reduce these possible side effects." (PMID 39594778, 2024). "Similarly, FOXM1 is mainly expressed in highly proliferative cells, including tumor cells." (PMID 39020302, 2024). "Therefore, the topical application of thiostrepton could be an effective way of delivering this FOXM1 inhibitor to the tumor cells and alleviating the disease." (PMID 38374400, 2024). "In addition, the expression of LC3B in the tumor tissues was significantly inhibited in theFOXM1 knockdown group, as determined by immunofluorescence staining, confirming that FOXM1 could also promote autophagyin vivo." (PMID 39086352, 2024). "Thus, FOXM1 represents a critical target to tumor cells exhibiting CIN or aneuploidy." (PMID 37452072, 2023). "Moreover, elevation of FOXM1 message was associated with elevated expression of MYC and statistical comparison of paired baseline and progression samples from 65 patients revealed that FOXM1 underwent, on average, a ~2-fold upregulation during tumor progression." (PMID 35794249, 2022). "Therefore, in TMA of GC, the tumor-promoting effect of FOXM1 and EZH2 in tumor cells may be correlated to the upregulation of FAP in CAFs." (PMID 36401232, 2022). "Moreover, FOXM1 expression were significantly correlated with tumor invasion depth (P = 0.030)." (PMID 36401232, 2022). "Upon clinicopathological correlation, we found that co-overexpression of CENPF and FOXM1 in human HCCs was associated with more aggressive tumor behavior including presence of venous invasion, tumor microsatellite formation, and absence of tumor encapsulation." (PMID 35865168, 2022). "Therefore, we analyzed FOXM1 expression in our HGSOC patient tumor tissues by IHC on the TMAs." (PMID 35267428, 2022). "FOXM1 also may act as both direct and indirect targets for tumor therapeutic intervention." (PMID 35756697, 2022). "Hence, our findings imply that Artemisinin may exert its tumor suppressive effect in HCC cells by down-regulating FoxM1 and its downstream target genes." (PMID 34900697, 2021).
tumor (continued). "Therefore, we conclude that circ‐PRKDC and FOXM1 may have a synergistic effect on tumor growth, thereby participating in the tumorigenesis of CRC by regulating the miR‐198/DDR1 axis or in combination with miR‐375/FOXM1 and the Wnt/β‐catenin pathway." (PMID 34796685, 2021). "And berberine could significantly reduce the expression of FOXM1 in tumor (p < 0.05)." (PMID 35173608, 2021). "Mammalian transcription factor Forkhead Box M1 (FOXM1) belongs to the extensive family of Forkhead transcription factors, characterized by a conserved protein domain called Forkhead or winged-helix domain, which known as a key regulator in tumor growth and cell-cycle regulation." (PMID 33723252, 2021). "The hypothesized pro-tumor roles of AVIL specifically through the FOXM1/LIN28B axis is seen in." (PMID 34948433, 2021). "Finally, we verified whether hsa_circ_0042823 affected tumour growth of LSCC via miR-877-5p/FOXM1 axis." (PMID 34124974, 2021). "Finally, restoration of FOXM1 expression abolished the anti-tumour effects of USP28-silencing." (PMID 34584067, 2021). "Moreover, FOXM1 was positively correlated with MIAT expression in NSCLC tumor tissues." (PMID 32742195, 2020). "However, whether FoxM1 plays a role in tumour development by transcriptional regulation of ASPM expression is still unknown." (PMID 32667745, 2020). "We, therefore, asked whether HMGA1 and FOXM1 are involved in tumor angiogenesis." (PMID 31311575, 2019). "Additionally, all three FOXM1 isoforms had increased expression in paired tumor vs. normal samples." (PMID 30795624, 2019). "However, little is known about the possible role of FOXM1 in tumor microenvironment." (PMID 30208972, 2018). "In both solid and liquid cancers, FOXM1 governs a wide spectrum of biological processes, including cell cycle progression, DNA damage repair, self-renewal of stem cells and senescence – all involved in tumor progression and the response of malignancies to cytostatic and targeted treatments." (PMID 30463534, 2018). "In addition, patients with ICC who overexpress FoxM1 might have larger tumor burdens and earlier postoperative recurrence or metastasis." (PMID 30580327, 2018). "Of the 21 transcription factors regulated by miR-SX4, FoxM1 have been extensively reported to be involved in cell cycle progression and in regulation of cell survival genes; and its elevated expression is positively correlated with tumor progression and poorer prognosis of cancer." (PMID 29343703, 2018). "Taken together, FoxM1 might increase the ability of tumor-initiating cells in NPC." (PMID 30416986, 2018). "Our clinical data showed FoxM1 expression and nuclear β-catenin are concomitantly increased in EOC samples and their upregulated expression are significantly associated with advance stage tumor, prompted us to study the biological relevance of this interaction." (PMID 29423068, 2018). "Very recently, we identified FoxM1 expression in tumor tissues as an independent prognostic factor affecting recurrence of HCC and overall survival of HCC patients following surgery, indicating that FoxM1 might not only be a promising therapeutic target but also a prognostic biomarker for HCC." (PMID 29765517, 2018). "Also, the present study suggests that the expression of transcription factor FOXM1 in nuclei of tumor cells could be a potential predictive marker of response of mCRC patients to cetuximab therapy." (PMID 28423516, 2017). "In addition to CENPF down-regulation, IPA analysis suggested many targets involved in tumor-stromal interactions and tumor vascularity by a complex regulatory network that might contribute to the effects of FOXM1 depletion in this cellular model." (PMID 28482906, 2017). "The in vivo-specific down-regulation of FOXM1 suggests that ZR30 has the ability to alter the tumor micro-environmental cue to which the transcription of FOXM1 indirectly responds, which may result in a lower expression of IGFBP3 comparing to control, due to a less hypoxic environment." (PMID 29290950, 2017).
tumor (continued). "Therefore, the expression of FOXM1 in the tumor could be a potential predictive marker of response to cetuximab in CRC patients." (PMID 28423516, 2017). "Importantly, our data suggest that FOXM1 might be considered a valid target for combinatorial anticancer therapy, despite molecular and histological tumor heterogeneity." (PMID 28482906, 2017). "This analysis demonstrated that atypical tumours harbour a distinct expression profile of a set of transcripts, which were significantly enriched for cell cycle processes, including upregulation of the E2F and FOXM1 transcription factor networks (hypergeometric test)." (PMID 28195122, 2017). "FOXM1 may be involved in SS tumor progression in a variety of ways." (PMID 27439614, 2016). "Similarly, the in vivo xenograft model showed that overexpression of OTUB1 could accelerate the tumor growth speed and increase the tumor weight, which were both suppressed by knockdown of FOXM1 in spite of OTUB1 overexpression (p<0.01)." (PMID 27167337, 2016). "In particular, FOXM1’s role in endothelial cells and other host cells as reported may complicate the anticancer strategies targeting FOXM1 and suggests that specific tumor cells targeting is necessary." (PMID 26299613, 2015). "Our genetic experiments indicate that FOXM1 is particularly relevant for proliferation and survival of leukaemic B lymphoblasts but not normal B-cell development and survival and may, therefore, represent a tumour-specific therapeutic target." (PMID 25753524, 2015). "Moreover, FoxM1 expression is higher in tumor cells than surrounding stroma." (PMID 25426548, 2014). "Taken together, FoxM1 may play several significant functions in tumor cells." (PMID 23536876, 2013). "Having established that deletion of Foxm1 from lung epithelial cells prior to tumor initiation significantly reduced lung tumorigenesis, the next series of experiments were designed to determine whether Foxm1 was required during progression/expansion of lung tumors in vivo." (PMID 19672312, 2009). "FOXM1 is one of the main transcription factors that regulates PD-L1 expression and ICI immune response in tumors, and can increase the sensitivity of tumor cells to immunotherapy." (PMID 40589640, 2025). "As a TF, FOXM1 regulates angiogenesis by upregulating VEGF promoter activity, elevating VEGF mRNA and protein levels, and thus promoting angiogenesis, tumor proliferation, and invasion." (PMID 40612352, 2025). "Substantial reduction of tumor growth and metastasis in RPM model, further strengthens the utilization of FOXM1 as a therapeutic target for developing therapies for SCLC." (PMID 40630538, 2025). "In the M6A-dependent pathway, VIRMA regulates key oncogenes (e.g., FOXM1, HK2) and tumor suppressor genes (e.g., RND3, BTG2), affecting the proliferation, metastasis, metabolic reprogramming, and drug resistance of tumor cells." (PMID 40723784, 2025). "The expression of UBE2S in HIN and LIN was situated in the cytoplasm and nucleus, and the expression of HIF‐1α and FOXM1 in HIN and LIN was primarily situated in the nucleus of tumor cells." (PMID 41427004, 2025). "FOXM1, a transcription factor involved in cell proliferation, interacts with YAP through TEAD1 to regulate genes essential for tumor growth." (PMID 41256331, 2025). "ALKBH5 drives EMT in UM cells by demethylating Forkhead box protein M1 (FOXM1) mRNA, increasing its expression and stability, thereby promoting tumor progression." (PMID 41315216, 2025). "It has also been reported in ESCC that FOXM1 is significantly elevated in lesion tissue samples of individuals with ESCC and inhibition of FOXM1 can inhibit tumor progression; thus, it can be utilized as a selective target for treatment." (PMID 41427004, 2025). "FOXM1 is known to enhance CSC traits by promoting self-renewal, drug resistance, and tumor initiation." (PMID 40608151, 2025).